SHBG (sex hormone binding globulin)
Diseases named in the same sentence as SHBG in open-access papers (continued):
Sharing a sentence is not in itself a finding about the gene and the disease.
asthma (7 papers, 2015 to 2024). "Genetic evidence shows that RA, IBD, PBC, NAFLD, SLE, asthma and SHBG correlate with a heightened risk of OP." (PMID 39886030, 2024). "In this study, we present the first tentative evidence that increased circulating SHBG is causally associated with a decreased risk of asthma, with effects stronger in females." (PMID 30936389, 2019). "We have conducted a novel hybrid investigation of the associations of SHBG and testosterone with asthma using dual longitudinal data analysis and an MR design." (PMID 30936389, 2019). "Another MR study found a tendency for a lower risk of asthma with a higher SHBG concentration." (PMID 36434743, 2022). "When using IV combination B, similar evidence for a protective effect of SHBG on asthma was obtained in females, whereas these estimates largely agreed with estimates based on IV combination A in males." (PMID 30936389, 2019). "Further work is required to disentangle the downstream effects of SHBG on asthma and the molecular pathways involved." (PMID 30936389, 2019). "Serial cross-sectional models using multiple imputation and adjusted for previous measures of asthma and either SHBG, TT or BT demonstrated similar estimates to the base models." (PMID 30936389, 2019). "Genetic evidence using two-sample MR indicated a protective effect of increased SHBG on asthma, with the effects most evident among females and indications of horizontal pleiotropy in the more liberal combination of IVs." (PMID 30936389, 2019). "The differences in effects of SHBG on asthma between sexes observed have the potential to explain the increase in female asthmatics observed after puberty." (PMID 30936389, 2019). "For SHBG there was an OR for asthma of 0.96 (95% CI 0.74 to 1.24), 1.54 (95% CI 0.71 to 3.37), 1.32 (95% CI 0.64 to 2.70), 1.18 (95% CI 0.67 to 2.06) and 1.02 (95% CI 0.57 to 1.83) at 9.9, 11.8, 13.8, 15.5 and 17.8 years, respectively." (PMID 30936389, 2019). "Observational evidence indicated weak evidence of a protective effect of increased circulating testosterone on asthma in males in adolescence, but no strong pattern of association with SHBG." (PMID 30936389, 2019). "Whether the effects of sex hormones are meaningful as potential intervention targets is unknown and further work is required to disentangle the downstream effects of SHBG on asthma." (PMID 30936389, 2019). "We report the first suggestive evidence of a protective effect of genetically elevated SHBG on asthma, which may provide a biological explanation behind the observed asthma sex discordance." (PMID 30936389, 2019). "We have not been able to find any previous literature that has investigated the effect of circulating SHBG on asthma that could be used to facilitate comparisons with our MR estimated effects." (PMID 30936389, 2019). "Genetic evidence using two-sample MR indicated a protective effect of increased SHBG, with an OR for asthma of 0.86 (95% CI 0.74 to 1.00) for the inverse-variance weighted approach and an OR of 0.83 (95% CI 0.72 to 0.96) for the weighted median estimator, per unit increase in natural log SHBG." (PMID 30936389, 2019). "Future studies could attempt to develop methods to investigate time-varying exposures (eg, SHBG) on time-varying outcomes (eg, asthma) in an MR framework." (PMID 30936389, 2019). "It was therefore not possible to determine if SHBG is causal to the ‘adolescent switch’ observed in asthma prevalence or if the decreased risk is an unrelated early-life or later-life effect of SHBG on asthma." (PMID 30936389, 2019). "For females, there was an IVW estimated 0.80 (95% CI 0.63 to 1.01) OR for asthma per unit increase in log SHBG when using IV combination A, whereas in males there was an IVW estimated 0.95 (95% CI 0.77 to 1.18) OR for asthma." (PMID 30936389, 2019).
asthma (continued). "Changes in circulating sex hormone levels and sex hormone-binding globulin (SHBG) have been described in patients with atopic dermatitis, asthma, hereditary angioneurotic oedema, and chronic urticaria." (PMID 25756057, 2015). "Observational evidence indicated some evidence of a protective effect of increased TT on asthma, but no clear pattern for SHBG." (PMID 30936389, 2019). "The effects of other hormones that could influence asthma physiology, such as testosterone and sex hormone-binding globulin, were not investigated in this study, and estrogen levels were not directly measured." (PMID 35203202, 2022). "Although previous hypotheses have suggested an immunological/inflammatory effect of SHBG on asthma, MR does not distinguish between which mechanistic pathways link the exposure to the outcome." (PMID 30936389, 2019).
colorectal cancer (7 papers, 2014 to 2025). A primary or metastatic malignant neoplasm that affects the colon or rectum. "For example, testosterone bound to sex hormone-binding globulin (SHBG), another megalin ligand, is associated with reduced risk of colorectal cancer in men." (PMID 25036524, 2014). "A limited number of MR studies have explored the potential causal associations between estradiol, bioavailable testosterone, total testosterone and SHBG, and lung and colorectal cancer risks in women." (PMID 39396092, 2024).
Glucose intolerance (7 papers, 2018 to 2023). Glucose intolerance (GI) can be defined as dysglycemia that comprises both prediabetes and diabetes. "There is a close relationship between insulin sensitivity and testosterone concentrations in men across a wide range of glucose intolerance, including those with T2DM, and independent of SHBG concentrations." (PMID 29566712, 2018).
hypertriglyceridemia (7 papers, 2014 to 2025). A laboratory test result indicating elevated triglyceride concentration in the blood. "In the present study, low SHBG levels were associated with hypertriglyceridemia and low HDL cholesterol levels in postmenopausal women, which is consistent with previous research." (PMID 40495241, 2025). "Specifically, low SHBG levels correlated with hypertriglyceridemia and low high-density lipoprotein levels." (PMID 40495241, 2025). "In addition, after using HOMAIR and SI as covariates, results still revealed that hyperinsulinaemia and possibly a low SHBG level are the main factors influencing postprandial hypertriglyceridaemia." (PMID 26989412, 2016). "Additionally, hypertriglyceridemia may reduce sex hormone-binding globulin (SHBG) levels, leading to increased free estrogen concentrations and further promoting PCa progression." (PMID 40746535, 2025).
rheumatoid arthritis (7 papers, 2020 to 2024). A chronic, systemic autoimmune disorder characterized by inflammation in the synovial membranes and articular surfaces. "Emerging evidence suggests that sex hormones, particularly testosterone and sex hormone-binding globulin (SHBG), play a critical role in the pathophysiology of Rheumatoid arthritis (RA)." (PMID 39759528, 2024). "With genetic instruments from JMJD1C and SHBG regions, a two-sample Mendelian randomization study found that low levels of testosterone may cause gout and type II diabetes (T2D), while testosterone higher than normal levels may result in rheumatoid arthritis (RA) and depression." (PMID 36482455, 2022). "Consistently, SHBG levels rebounded in patients with chronic inflammatory states, such as rheumatoid arthritis, using a TNF-α inhibitor." (PMID 35493382, 2022). "Our study aims to investigate an intrinsic link underlying sex hormone-binding globulin (SHBG) and rheumatoid arthritis (RA), which remains inconclusive in observational settings." (PMID 37644603, 2023). "Sex hormone-binding globulin (SHBG) has been reported to be a risk factor associated with the development of arthritis by previous observational studies more so of three common forms of arthritis: osteoarthritis (OA), rheumatoid arthritis (RA), and ankylosing spondylitis (AS)." (PMID 32423484, 2020).
schizophrenia (7 papers, 2013 to 2025). A major psychotic disorder characterized by abnormalities in the perception or expression of reality. "The five frequently selected interactions suggest that the sex of a subject was modifying the effects of peptides from APOE, A2AP, HBA, HBG1, and SHBG on the probability of having schizophrenia." (PMID 30745560, 2019). "Model selection using glinternet to allow for first-order interactions identified five peptides from APOE, A2AP, HBA, HBG1 and SHBG whose effect on the probability of having schizophrenia was modified by sex." (PMID 30745560, 2019). "Decreased SHBG has been reported in female schizophrenia patients after treatment with atypical antipsychotics, in association with increased prolactin levels." (PMID 24244349, 2013). "While genetic correlations do not reflect causal relationships and do not control for pleiotropy and potential confounding, we interestingly identified a Bonferroni-significant positive genetic correlation between SHBG levels and schizophrenia, suggesting these have a partially shared genetic basis." (PMID 40727568, 2025). "Future studies may consider assessing the impact of sex hormone binding globulin and other circulating hormones such as corticosteroid, thyroid hormones and estrogen on brain activity in schizophrenia." (PMID 24204845, 2013).
androgenetic alopecia (6 papers, 2018 to 2025). "Studies have shown that SHBG levels inversely correlate with androgenetic alopecia severity." (PMID 41394121, 2025). "We assessed genetic associations of variants in two gene regions (SHBG and JMJD1C) with several cardiovascular risk factors (lipids, adiponectin, blood pressure, anthropometric traits) plus male pattern baldness, including control outcomes and potential mediators." (PMID 29804699, 2018).
gastric cancer (6 papers, 2018 to 2025). A primary or metastatic malignant neoplasm involving the stomach. "Evidence may suggest a sex-specific link of T or SHBG with liver cancer, stomach cancer, and melanoma, with higher T associated with elevated risk." (PMID 41228208, 2025). "However, one study indicated that elevated SHBG was associated with increased gastric cancer incidence in men only." (PMID 41228208, 2025). "Additionally, polymorphisms in SHBG and catechol-O-methyltransferase, involved in estrogen inactivation, have been associated with gastric cancer risk." (PMID 37455285, 2023). "SHBG is synthesized in the liver and has an important role in modulating sex hormone levels; it is up-regulated in the blood serum of both colorectal and gastric cancer patients." (PMID 31355141, 2019).
osteoarthritis (6 papers, 2020 to 2025). A noninflammatory degenerative joint disease occurring chiefly in older persons, characterized by degeneration of the articular cartilage, hypertrophy of bone at the margins and changes in the synovial membrane. "A Mendelian randomization study has also demonstrated a positive causal relationship between sex-hormone-binding globulin (SHBG) and osteoarthritis." (PMID 40270731, 2025). "A recent study used MR analysis to discover ten circulating proteins, including SHBG, which is causally associated with traits associated with osteoarthritis (OA)." (PMID 39206315, 2024). "Eight markers were found to be associated with an increased risk of osteoarthritis, including serum testosterone, serum dihydrotestosterone, sex hormone-binding globulin, glycosylated hemoglobin (HbA1c), insulin-like growth factor-binding protein 4, lipocalin, leptin, and resistin." (PMID 39172202, 2024). "The correlation between lowered levels of SHBG and inflammatory process indicates that not only metabolic disorders but also other pro-inflammatory diseases like osteoarthritis, bowel diseases, cancers, or allergies can have an influence on SHBG and serum levels of sex hormones." (PMID 40427034, 2025).
Stroke (6 papers, 2021 to 2025). Sudden impairment of blood flow to a part of the brain due to occlusion or rupture of an artery to the brain. "This suggests elevated WC, WHR, and TG in turn lower circulating SHBG levels, increasing the stroke risk." (PMID 40728963, 2025). "Our findings suggest a protective effect of genetically elevated SHBG levels on stroke risk via key cardiometabolic mediators, primarily WC, WHR, and TG." (PMID 40728963, 2025). "Based on the findings detected from the discovery and replication GWAS datasets, WC, WHR, FG, T2DM, TG, SBP, and DBP were considered as the potential cardiometabolic mediators of the causal pathways from SHBG levels to stroke risk." (PMID 40728963, 2025). "A network two-sample Mendelian randomization (MR) study was conducted to determine the mediating roles of cardiometabolic traits in the causal effects of SHBG levels on stroke subtypes." (PMID 40728963, 2025). "Nevertheless, conventional epidemiological studies are susceptible to residual confounding, reverse causality, or exposure measurement errors, making the causal associations between SHBG levels and stroke risk elusive or conflicting." (PMID 40728963, 2025). "More importantly, recent GWASs have identified multiple polymorphisms related to circulating SHBG levels, thus providing a valuable opportunity to explore the causal relationship between SHBG levels and stroke risk using MR approaches." (PMID 40728963, 2025). "These causal findings suggest SHBG as a promising biomarker and therapeutic target in stroke prevention." (PMID 40728963, 2025). "Given the limitations of observational studies, MR offers an alternative approach to assess the causality between SHBG levels and stroke outcomes." (PMID 40728963, 2025). "The causal nature of sex hormone-binding globulin (SHBG) in the pathogenesis of stroke remains uncertain." (PMID 40728963, 2025). "Some previous studies reported that the association between SHBG and stroke can be attributed to several mediating factors such as BMI." (PMID 38596080, 2024). "In the present study, bi-directional and multivariable MR analyses (MVMR) were conducted to explore the causal relationship between SHBG and stroke (and its subtypes)." (PMID 38596080, 2024). "It is known that SHBG can regulate the level of bioavailability of sex hormones such as testosterone and estradiol, which have been implicated in stroke risk." (PMID 38596080, 2024). "Our MR study provides novel evidence that SHBG has an inverse association with stroke and ischemic stroke, exerting protective effects on stroke." (PMID 38596080, 2024). "The heterogeneity was detected in Cochran's Q statistics (P < 0.05), and the random effects IVW method was further applied to estimate the causal effect between SHBG and its stroke subtypes." (PMID 38596080, 2024). "In our MR analyses, statistically significant inverse association between SHBG and stroke, and IS was noted." (PMID 38596080, 2024). "Collectively, we considered that WC, WHR, T2DM, TG, SBP, and DBP could partially mediate the pathways from lower SHBG levels to the risk of any stroke, ischemic stroke, or small-vessel stroke." (PMID 40728963, 2025). "Second, as the measured SHBG levels and stroke diagnostic criteria may be heterogeneous across ancestries, our study only included European individuals to minimize population stratification, which would limit generalizability to some degree." (PMID 40728963, 2025). "The MR network analyses suggested that genetically determined WHR, SBP, and DBP may be the common mediators of the associations between SHBG levels with any stroke, ischemic stroke, and small-vessel stroke, and the mediating effects ranged from 17.8% to 52.7%." (PMID 40728963, 2025). "After removing the outlier SNPs or the possible pleiotropic SNPs detected by the MR-PRESSO method orGWAS catalog, no significant heterogeneity was observed in these causal associations between SHBG levels and stroke risk (all I2 < 25% or Cochran Q-derived p > 0.05)." (PMID 40728963, 2025).
Stroke (continued). "To further examine whether SHBG also mediated the causal effects of cardiometabolic traits on stroke, we assessed the causal associations between the potential cardiometabolic mediators and SHBG levels using IVs in the discovery datasets (for the MR design)." (PMID 40728963, 2025). "Our study highlighted a protective effect of genetically increased SHBG levels on stroke risk via key cardiometabolic mediators, primarily WC, WHR, and TG; moreover, the mediating roles of SHBG levels in the causal links from WC, WHR and TG to stroke risk were also established." (PMID 40728963, 2025). "The underlying mechanisms between SHBG and metabolic disorders or stroke may involve activation of the inflammatory response, accelerating lipid accumulation in macrophages and adipocytes, or increasing free testosterone with downstream pro-androgenic effects." (PMID 40728963, 2025). "Moreover, the causal association between SHBG and stroke cannot be concluded based on previous studies." (PMID 38596080, 2024). "We found that the risk of stroke grew by 13% (odd ratio [OR] = 0.87, 95% confidence interval [CI] = 0.79–0.95, P = 0.0041) and the risk of ischemic stroke grew by 15% (OR = 0.85, 95%CI = 0.77–0.95, P = 0.0038) caused by genetically predicted SHBG." (PMID 38596080, 2024). "Finally, the application of SHBG test can be easily used as a effective tool to screen individuals with a high stroke risk." (PMID 38596080, 2024). "This is the first MR study to illuminate the causal association between SHBG and stroke (subtypes)." (PMID 38596080, 2024). "Therefore, we hypothesized that these conventional cardiometabolic traits may be involved in the causal pathway from SHBG level to stroke risk." (PMID 40728963, 2025). "We explored whether SHBG levels are causally associated with stroke via cardiometabolic traits." (PMID 40728963, 2025). "Therefore, incorporating SHBG levels into stroke risk prediction models, particularly when stratified by sex, could provide valuable insights into the interplay between SHBG and stroke." (PMID 38596080, 2024). "Our study provides novel genetic insights that SHBG may play a protective role in stroke risk." (PMID 38596080, 2024). "In the reverse MR direction, the mediating proportions of SHBG levels in the causal associations between WC, WHR, and TG with any stroke, any ischemic stroke, or small-vessel stroke ranged from 18.4 to 68.3%." (PMID 40728963, 2025). "The mediating roles of SHBG levels in the causal links from WC, WHR and TG to stroke risk were also established." (PMID 40728963, 2025). "In addition, SHBG could markedly suppress lipopolysaccharide-induced inflammatory biomarkers in macrophages and adipocytes, such as monocyte chemoattractant protein-1, TNFα, and IL-6, which have been reported to be closely related to stroke risk and prognosis." (PMID 40728963, 2025). "As expected, our study found genetically determined SHBG levels were causally associated with a lower risk of WC, WHR, T2DM, TG, SBP, and DBP, which further reduced the risk of any stroke, ischemic stroke, or small-vessel stroke." (PMID 40728963, 2025). "This suggests that SHBG also plays a key role in mediating the causal associations between WC, WHR, and TG with stroke risk." (PMID 40728963, 2025). "The role of sex hormone-binding globulin (SHBG) on stroke has been investigated in several observational studies." (PMID 38596080, 2024). "49-54In our MR analysis, protective effects of SHBG on stroke are increased after adjusting DSL, EL, HDL-C, and BMI." (PMID 38596080, 2024). "In this study, our findings demonstrate that SHBG exerts a protective effect on stroke and IS [12,]." (PMID 38596080, 2024). "Although a potential link between SHBG and stroke is established in our study, our results cannot fully explain specific biological mechanisms related to protective effects of SHBG on stroke." (PMID 38596080, 2024).